MET (MET proto-oncogene, receptor tyrosine kinase)
Diseases named in the same sentence as MET in open-access papers (continued):
Sharing a sentence is not in itself a finding about the gene and the disease.
gastric cancer (continued). "Nevertheless, it was surprising to us that MET inhibitors had no measurable effects in the gastric cancer cell lines that contained activating MET mutations." (PMID 28881678, 2017). "PD-L1 expression was observed in 123 cases (31.2%), and clinicopathological features such as MET overexpression, high pT stage, and a lack of lymphatic invasion represent significant risk factors associated with PD-L1 overexpression in gastric cancers." (PMID 29137273, 2017). "Because of this complexity, and the interest in targeting autophagy to improve the effects of cancer therapies, it was important to understand what role autophagy activation played in apoptosis induced by MET inhibition in the MET-amplified gastric cancer cells." (PMID 28881678, 2017). "The partial response rate was 14.3% (two of 14) in gastric cancer patients with MET amplification." (PMID 29108334, 2017). "MET overexpression could serve as a prognostic biomarker and a potential therapeutic target for gastric cancer." (PMID 28052014, 2017). "MET expression has been reported in many tumor types, including gastric cancer." (PMID 29071414, 2017). "Autophagy inhibitors promoted cell death in cancer cells exposed to other pro-apoptotic agents, raising the possibility that autophagy inhibitors might promote the effects of MET antagonists in human gastric cancer cells." (PMID 28881678, 2017). "A marked heterogeneity of MET amplification in distinct tumor lesions within a single gastric cancer patient has been reported, and this heterogeneity may be a key driver of resistance to c-Met inhibitors." (PMID 29108334, 2017). "Despite these efforts, only a few genetic changes, including the amplification and/or overexpression of MET and ERBB2, as well as the mutations and downregulation of APC and RUNX3, have been associated with gastric cancer and the underlying molecular mechanisms remain largely undefined." (PMID 26942872, 2016). "In addition, MET/p-MET expression was significantly observed in HER2-positive gastric cancer tissues." (PMID 26716644, 2016). "If these findings can be translated into gastric cancer settings, patients with high expression of MET, FGFR1 and ERBB2 may exhibit EGFR therapeutic resistance." (PMID 27738318, 2016). "In this study, adding HGF to lapatinib treatment in MET-overexpressed HER2 gastric cancer cells not only activated MET, but also led to restimulation of downstream effectors AKT and ERK1/2 even in the presence of lapatinib, although phosphorylation of HER2 and EGFR continued to be suppressed." (PMID 26716644, 2016). "MET IHC 3+ expression was associated with a shorter OS and PFS, and MET gene copy number detected by FISH correlated with MET protein expression detected by IHC in gastric cancer patients." (PMID 27013592, 2016). "Together with earlier studies, the data suggest that MET amplification may represent a critical genetic aberration in gastric cancers and this patient population could benefit from treatment with ABT-700." (PMID 26879245, 2016). "Preliminary data from other studies have suggested that MET amplification can identify subgroups of patients with lung or gastric cancer who may benefit from MET inhibitors, suggesting that MET amplification as a may represent a putative biomarker." (PMID 25965822, 2015). "MET, also known as hepatocyte growth factor receptor (HGFR), is a receptor tyrosine kinase (RTK) that is overexpressed and/or mutated in a variety of malignancies, including gastric cancer." (PMID 25874496, 2015). "Our results clearly demonstrate that MET gene copy number increases in PRCC tumors are highly associated with increases in the copy number of Chromosome 7, which differs from previous observations in lung and gastric cancer." (PMID 26636767, 2015). "Considering the high proportion of sf-RON overexpresson in MET+ gastric cancer samples, activation of this pathway might serve as a crucial signaling compensatory mechanism that attenuates the efficacy of anti-MET therapy." (PMID 26528757, 2015).
gastric cancer (continued). "Furthermore, it was reported that MET gene amplification and overexpression predicted the sensitivity to MET inhibitors in gastric cancer." (PMID 26622787, 2015). "Besides HER2, other potential targets in gastric cancer, such as c-MET, PD-1/PDL-1, and IGFR, will be detected in the following study." (PMID 25712750, 2015). "Moreover, several clinical trials have shown clinical benefits from inhibition of the pathway of MET in patients with gastric cancer." (PMID 24416238, 2014). "Many retrospective studies have evaluated whether overexpression of MET is a prognostic factor for survival in patients with gastric cancer." (PMID 24416238, 2014). "To investigate whether attenuation of MET signaling by the MET-TKIs is related to the induction of apoptosis, we transfected gastric cancer cell lines with an siRNA specific for MET mRNA." (PMID 23327903, 2013). "To investigate the biological impact of MET amplification in gastric cancer, we first examined the effects of two highly selective MET receptor tyrosine kinase inhibitors (MET-TKIs), JNJ38877605 and SGX523, on the growth of gastric cancer cell lines positive or negative for MET amplification." (PMID 23327903, 2013). "In gastric cancer, such activation of MET has been attributed to gene amplification." (PMID 23327903, 2013). "Moreover, to assess the potential of MET amplification as a therapeutic target in gastric cancer, we investigated its impact on cell survival and signal transduction." (PMID 23327903, 2013). "Given the potential of MET-targeted therapy for gastric cancer with MET amplification, it is important to determine the prevalence of such gene amplification in patients with unresectable advanced gastric cancer, most of whom are currently treated with systemic chemotherapy." (PMID 23327903, 2013). "Indeed, the MET-TKI crizotinib (PF-02341066) was recently found to induce a radiographic response (partial response) and rapid clinical improvement in patients with advanced gastric cancer who were found to be positive for MET amplification by FISH." (PMID 23327903, 2013). "Given that the HGF/MET pathway is highly activated in gastric cancer, it is biologically plau-sible that the MET S375 variant with a low affinity for HGF may reduce gastric cancer risk, which is con-sistent with our findings." (PMID 23554766, 2012). "Preclinical studies have shown that BMS-777607 delays the growth of human gastric cancer xenografts with MET gene amplification, inhibits HGF-induced metastasis-related functions in prostate cancer cells, and impairs pulmonary metastases in a rodent sarcoma model with hyperactivated c-Met." (PMID 22639908, 2012). "The MET signaling pathway plays a critical role in various cancers, and the disruption of the balance of MET and HGF has been implicated in the etiology and progression of multiple cancers, including gastric cancer." (PMID 23554766, 2012). "To evaluate this hypothesis, we genotyped 137 SNPs in seven candidate genes and demonstrated that genetic variants of SRC (rs6122566 and rs6124914), c-MET (rs41739) and CRK (rs7208768) were significantly associated with gastric cancer risk." (PMID 22383989, 2012). "c-MET overexpression and amplification have been reported in 18-82% of gastric carcinoma which studied by immunofluorescence, immunohistochemistry (IHC), reverse transcription polymerase chain reaction (RT-PCR), Northern blot analysis and Southern blot analysis." (PMID 22640970, 2012). "To examine whether the activation of MET contributes to STAT3 activation, we determined the effects of the MET-TKI PHA-665752 on the phosphorylation of STAT3 in gastric cancer cells with STAT3 activation." (PMID 21730976, 2011). "Moreover, we show that an in vitro generated gastric cancer cell line resistant to MET-inhibition displays overexpression of HER family members, whose activation contributes to maintenance of resistance." (PMID 20500904, 2010).
gastric cancer (continued). "However, MET amplification is relatively rare, occurring in only 2–10.2% of gastric cancers." (PMID 40860829, 2025). "MET overexpression is associated with poor survival in non-small-cell lung cancer, while c-Met has been tested for use as a therapeutic target using c-Met inhibitors in gastric cancer." (PMID 40940954, 2025). "In this study, we aimed to determine the effects of these inhibitors on MET-amplified gastric cancer (GC) cells." (PMID 38892160, 2024). "Potentially only MET amplification detected by comprehensive genomic testing could be a good targeted option, although the prevalence is limited to less than 5% of all patients with gastric cancer." (PMID 37046637, 2023). "Therefore, the combination therapy of MET and FGFR2 inhibitors may be a promising strategy to treat the inherent resistance of MET inhibitors in gastric cancer cases containing MET and FGFR2 amplification." (PMID 35664756, 2022). "Moreover, TRIM62, MET, and HBA1, which were significantly associated with oxidative stress, may be biomarkers for the prognosis of gastric cancer." (PMID 35659682, 2022). "Research has shown that oxidative stress is increased in T cells and decreased in mucous cells in the gastric cancer microenvironment, while TRIM62, MET and HBA1, which are associated with oxidative stress, may be biomarkers reflecting the prognosis of gastric cancer." (PMID 36439106, 2022). "In this study, we characterized the expression of MET (including METex14SM), PD-L1, and CD44 in human gastric cancer (GC) cells as well as the differential susceptibility of these cells to tepotinib." (PMID 35884507, 2022). "Therefore, MET amplification in ctDNA may predict disease progression in patients with advanced gastric cancer in the same way as MET amplification in tumor tissues." (PMID 33959414, 2021). "In addition to the potential differential response of MET overexpressed tumor cells to chemotherapy, changes in MET expression may be due to tumor heterogeneity in gastric cancer, which is currently considered as a major challenge to cancer treatment." (PMID 34557411, 2021). "Thus, we hypothesized that SATB1 could also be involved in HER-dependent resistance mechanisms upon MET inhibition in gastric cancer cells." (PMID 33374770, 2020). "Furthermore, H. pylori infection-induced activation of MET may affect the immune cells that surround gastric cancer cells." (PMID 33217986, 2020). "In addition, c-MET expression is a candidate for targeted therapy in gastric cancer." (PMID 30871613, 2019). "Interestingly, p-MET amplified gastric cancer cell lines belong to the diffuse-type." (PMID 30871613, 2019). "Therefore, the amplification of MET is confirmed as a resistance factor in gastric cancer cells." (PMID 31557260, 2019). "In another report, miR-34a could inhibit EMT in gastric cancer by targeting c-MET and Snail." (PMID 30360560, 2018). "The c-MET inhibitor SU11274 may suppress peritoneal mass in gastric cancer nude xenograft model." (PMID 30360560, 2018). "In human gastric cancer, MET amplification ranges between 4% and 23%; it remains to be determined whether MET amplification is a clinically important resistance factor for gastric cancer patients treated with afatinib in clinical trials." (PMID 29325228, 2018). "Since PD-L1/MET expression can be easily assessed in routinely processed tissue samples by immunohistochemistry, it could be employed as a promising prognostic tissue marker for patients with gastric cancer after resection." (PMID 29137273, 2017). "A pan-HER inhibitor, PF0029984, was tested in seven gastric cancer cell lines, each having one of the following abnormalities: KRAS mutation; amplification of FGFR2, MYC (V-Myc avian myelocytomatosis viral oncogene homolog) or MET (MET proto-oncogene receptor tyrosine kinase)." (PMID 29872697, 2017). "Therefore, MET overexpression could serve as a prognostic biomarker and a potential therapeutic target for gastric cancer." (PMID 28052014, 2017).
gastric cancer (continued). "Therefore, combined analyses of PD-L1 and MET expression may provide an accurate prediction for the prognosis of patients with gastric cancer." (PMID 29137273, 2017). "Clinicopathological features such as MET overexpression, high pT stage, and a lack of lymphatic invasion were revealed to be significant risk factors that can be used to predict PD-L1 overexpression in gastric cancers." (PMID 29137273, 2017). "Although MSI-H gastric cancers are hyper-mutated, MSS gastric cancers also possess a high frequency of genetic alterations such as CDH1, RHOA, HER2, EGFR, VEGFR, MET, and FGFR2, all of which may directly or indirectly affect the MAPK and PI3K/Akt survival pathways." (PMID 29137273, 2017). "MET gene amplification has been described in gastric cancer (GC) and hepatocellular carcinoma (HCC), which results in dysregulation of MET signaling and is associated with clinical prognosis and poor outcome." (PMID 26765781, 2016). "MET gene amplification has been reported in 1.5 to 10.2% of gastric cancers (GCs), and overexpression of MET can be detected in more than 20% of GC samples." (PMID 26528757, 2015). "To further speculate the reason, we used three types of c-MET altered cancer cell lines including SNU-5, MKN-45, and SNU-638 gastric cancer cells (c-MET amplification), NCI-H596 non-small cell lung cancer (c-MET splice mutation) and HT-29 colon cancer cells (c-MET overexpression)." (PMID 25193856, 2014). "Signal transducer and activator of transcription 3 activation by various receptor tyrosine kinases has previously been shown to be JAK dependent or JAK independent; however, it is unclear whether STAT3 is phosphorylated through JAK in MET-activated gastric cancer cell lines." (PMID 21730976, 2011). "Of interest, the pharmacological effect of MET-TKI for MET-amplified NSCLC and gastric cancer cells was predominantly reduced under HGF-enriched conditions; however, additional inhibition of active HGF overcame resistance." (PMID 40076928, 2025). "Co-expression of FGFR2 and other relevant biomarkers in gastric cancer, such as HER2, EGFR, MET, and Claudin 18.2, has also been a topic of interest." (PMID 41303727, 2025). "While MET inhibitors such as crizotinib have shown efficacy in MET-altered non-small cell lung cancer (NSCLC), their role in gastric cancer remains uncertain due to tumor heterogeneity and the lack of robust clinical evidence." (PMID 40860829, 2025). "Overall, the study supports MET and AXL as prognostic biomarkers and highlights LY2801653 as a promising therapeutic option for gastric cancer." (PMID 41011010, 2025). "For our study, we selected five gastric cancer cell lines with diverse genetic profiles—such as MET amplification in MKN45 cells and HER2 amplification in MKN7 cells—to represent the heterogeneity commonly observed in gastric cancer." (PMID 40846695, 2025). "Dual MET/Axl inhibitors, such as LY2801653 and CT053PTSA, have shown promising activity in gastric cancer models and early-phase trials." (PMID 41011010, 2025). "On the other hand, miR-206 mediates the regulation of c-MET, IGF1R, and MAPK3’s expression in gastric cancer." (PMID 38200584, 2024). "In gastric cancer cells, NPS-1034 inhibited the viability and clonogenicity of the high MET-expressing cell lines MKN45 and SNU638 and induced apoptosis in MKN45 cells." (PMID 39000029, 2024). "Consistent with other findings linking MET and EGFR oncogenic signaling, the resistance to MET inhibitors in lung and stomach carcinoma cells was accounted by NRP1-dependent EGFR upregulation." (PMID 39769452, 2024). "In this study, a combination of MET (tepotinib or PHA665752) and autophagy inhibition (3-MA) in gastric cancer cells significantly decreased cell viability." (PMID 36999986, 2023). "We have encountered a rare subset of gastric cancer patients with both FGFR2 and MET amplification on the same tumor specimen." (PMID 38137393, 2023).
gastric cancer (continued). "Among gastric cancer patients, 39 (6.4%) patients had FGFR2 amplification, and 22 (3.6%) patients had MET amplification." (PMID 38137393, 2023). "Our study findings are in line with previous research, reaffirming the prognostic significance of MET and FGFR2 amplification in gastric cancer." (PMID 38137393, 2023). "MET amplification was determined by NGS or FISH and an ORR of 50% was reached, showing the possible potential for cMET inhibitors in gastric cancer in a well-defined population." (PMID 37046637, 2023). "These incidence findings were consistent with previous studies, with MET amplification reported in 4–10% of cases and FGFR2 amplification in 4–15% of gastric cancer cases." (PMID 38137393, 2023). "For decades, the only known MET gene rearrangement in human tumors has been TPR-MET, mostly occurring in gastric cancers." (PMID 37760640, 2023). "Numerous studies consistently link MET and FGFR2 amplification with advanced tumor stages, metastasis, and poorer survival outcomes in gastric cancer." (PMID 38137393, 2023). "In 100 patients with gastric cancer, the expression of HGF and MET was higher in patients with more advanced disease as well as peritoneal metastasis showing that it plays an important role in epithelial-mesenchymal transition." (PMID 37046637, 2023). "We aimed in the current study to find the frequency of MET and FGFR2 amplification and their impact on gastric cancer treatment based on real-world data." (PMID 38137393, 2023). "In vivo, the antitumor efficacy of tepotinib was tested in mice bearing human tumor xenografts, representing various mechanisms of MET activation across multiple indications, including NSCLC and gastric cancer." (PMID 36999986, 2023). "In summary, our review underscores the critical molecular pathways driving gastric cancer progression, including the MAPK, PI3K/AKT/mTOR, HGF/c-MET, and Wnt/β-catenin pathways." (PMID 37894443, 2023). "EGFR and HER2 are the most recognized tyrosine kinase receptors in gastric cancer, while overexpression of other recognized tyrosine kinase receptors in gastric cancers includes fibroblast growth factor receptor 2 (FGFR2) and MET." (PMID 38186572, 2023). "Savolitinib is a MET inhibitor that has been developed to treat metastatic NSCLC, PRCC, gastric cancer, and CRC." (PMID 38077251, 2023). "When we assessed the expression status of individual gastric cancer oncogenes (e.g., CEACAM6, EGFR, MET, CCND1, and KRAS) among the tumor epithelial clusters, the EpiInt1 tumor epithelial cluster exhibited the largest increase." (PMID 34642171, 2022). "The gastric cancer group with N0 or N1 metastasis formed clusters with high expressions of ERBB2 mRNA and MET mRNA." (PMID 35650563, 2022). "For example, a 2021 report of results from the AcSé-crizotinib program indicated a role for c-MET inhibition in MET-amplified esophageal and gastric cancers." (PMID 35129063, 2022). "Our analysis also provides potential biomarkers for prognostic survival analysis of gastric cancer related to oxidative stress: TRIM62, MET, and HBA1." (PMID 35659682, 2022). "MACC1 can activate hepatocyte growth factor (HGF), and the activated HGF can easily bind to c-MET, which promote the phosphorylation of c-MET, thereby inducing the proliferation and invasion of gastric cancer." (PMID 35874635, 2022). "miR-34a is downregulated in gastric cancer and targets PDGFR and MET through the PI3K/Akt pathway to inhibit tumorigenesis of gastric cancer." (PMID 34957298, 2021). "Obviously, YES1, MET, and AXL activation in HER2-driven gastric cancer cells is a new mechanism for producing resistance, while the use of the corresponding activation inhibitor is a reliable method." (PMID 34976824, 2021). "This study also demonstrated a concomitant overexpression of MET and HER2 in a subset of patients with gastric cancers." (PMID 34557411, 2021). "Among the 90 gastric cancers, 10 cancers had gene amplification of one of ERBB2, KRAS, PIK3CA, and MET." (PMID 34873204, 2021).